ORAI3 (ORAI calcium release-activated calcium modulator 3)
Diseases named in the same sentence as ORAI3 in open-access papers (continued):
Sharing a sentence is not in itself a finding about the gene and the disease.
cancer (continued). "Considering the differences in redox-sensitivity between Orai1, Orai2, and Orai3, the ratio between the isoforms might be an interesting factor regulating Ca2+ signals under oxidative stress conditions during pathophysiological situations like cancer." (PMID 30935064, 2019). "Indeed, our studies show that ORAI3 is induced in a variety of cancer models by hypoxia." (PMID 30754719, 2019). "This study has identified MARCH8 as a critical regulator of Orai3, which we had earlier reported as a driver of PC metastasis Although MARCH8 E3 ubiquitin ligase has been studied in some cancer types, its role in PC remains largely unappreciated." (PMID 41023307, 2025). "Orai3 promotes cancer stem-like cell phenotypes by upregulating the stemness transcription factor ID1, suggesting that the Orai3/ID1 axis is a novel regulatory mechanism for maintaining cancer stemness in OSCC." (PMID 39759147, 2024). "Our study reveals that Orai3 is a novel functional CSC regulator in OSCC and further suggests that Orai3 plays an oncogenic role in OSCC by promoting cancer stemness via ID1 upregulation." (PMID 37759448, 2023). "In this current research, we introduce a novel finding: the elevated expression of Orai3 in oral and oropharyngeal carcinogenesis occurs in a gradual fashion and is notably concentrated within OSCC CSC (cancer stem-like cell) populations." (PMID 37759448, 2023). "Based on numerous previous studies, Orai channels (Orai1, Orai2 and Orai3 channels) control Ca2+ release-activated Ca2+ (CRAC) currents and contribute to SOCE currents in other types of cells, including various cancer cells." (PMID 37759164, 2023). "Further, examination of E-cadherin upon Orai3 silencing suggests that Orai3 modulates EMT, an essential step in cancer metastasis." (PMID 34885048, 2021). "Many pathophysiological cellular functions in aging and cancer involve SOCE and Orai3, highlighting the importance of understanding the pharmacology of Orai1/Orai3 heteromeric SOCE channels." (PMID 32252254, 2020). "In order to unravel the molecular underpinnings of constitutive Ca2+ entry, we undertook protein knockdown of Stim1, Orai1 and Orai3, that have been involved in SOCE activation in cancer cells, by using a siRNA silencing approach." (PMID 30123430, 2018). "Recently, studies also reported that Orai remodelling was happened in cancer cell through Orai1 and Orai3 tetramer replacing Orai1 tetramer and did not need STIM1 activation." (PMID 36128650, 2022). "In the investigated cells, Orai3 is predominantly overexpressed as compared to non-tumor cells but its role in SOCE/Ca2+ influx differs in the different cancer cell types." (PMID 34768857, 2021). "It is important to highlight that although Orai3 is reported to regulate cell migration in a variety of cancerous cells, the significance of Orai3 in driving cancer metastasis is not investigated earlier." (PMID 34885048, 2021). "Moreover, the increase of the transcriptional expression of Orai3, Nanog and SOX2 in CD133+-A549- and H23 cells when compared to nonsorted cells, demonstrates the increase in the population of cancer stem cells." (PMID 34065942, 2021). "Overexpression of functional Orai3 has been described in different neoplastic cells and cancer tissue samples as compared to non-tumor cells or normal adjacent tissue." (PMID 34768857, 2021). "In non-metastatic cancer cells, NFATc1 drives Orai3 transcription, increasing its levels." (PMID 41023307, 2025). "Overexpression of ORAI3 has been observed in various cancer cells as compared to normal cells." (PMID 36588677, 2022). "Besides the homomeric Orai3 channel, additionally, ARC or LTC4 channels, both heteromeric assemblies of Orai1 and Orai3, have been reported to trigger the development of certain types of cancer cells." (PMID 34360783, 2021). "Consequently, some cancers upregulate STIM-1 and ORAI-1 or ORAI3 to ensure a steady supply of low- to mid-level calcium, and cancer cells may become calcium-dependent." (PMID 29758025, 2018).
cancer (continued). "Additionally, the authors found that the relative expression level of the ORAI3 protein in cancer tissues was obviously higher than the level in noncancerous tissues." (PMID 27013185, 2016). "We show that Orai3 is over-expressed in cancer tissues as compared to the non-tumoral ones." (PMID 24058448, 2013). "However, there are no previous studies of hypoxia effects of ORAI3 in cancer cells." (PMID 30754719, 2019). "Furthermore, both the overall survival (OS) median and the metastasis free survival (MFS) median of tumors with high Orai3 expression were lower than in low Orai3 expression regardless of cancer stage (35.01 months vs. 51.11 months for OS and 46.01 months vs. 62.04 months for MFS)." (PMID 27835593, 2016). "In other cancer cells, such as the oral cancerous SAS cells, the expression of Orai3 is reduced in comparison with non-cancerous HaCaT cells, although the potential relevance of this finding has not been further explored." (PMID 34768857, 2021).
tumor (26 papers, 2013 to 2026). "Further, our extensive analysis of publicly available datasets clearly shows that higher Orai3 levels in PC tumor samples are associated with the lower mean survival time of PC patients." (PMID 34885048, 2021). "Univariate and multivariate regression analysis revealed that high expression of Orai3 was significantly associated with tumour necrosis, tobacco use, TTF1 expression, and visceral pleural invasion (OR: 5.03) and ERα expression (OR: 5.29) respectively." (PMID 27835593, 2016). "We further investigate whether the expression of Orai3 is associated to tumour aggressiveness." (PMID 27835593, 2016). "Lung adenocarcinoma (LUAD) exhibits pronounced ORAI3 upregulation relative to matched non-tumor tissue." (PMID 41596760, 2026). "To further examine the effect of Orai3 on tumor growth in vivo, we injected the cells into nude mice and observed tumor formation." (PMID 37759448, 2023). "Orai3 expression induced tumor sphere formation ability, indicating the acquisition of self-renewal capacity by Orai3." (PMID 37759448, 2023). "Orai3 was highly enriched in tumor spheres compared with their corresponding monolayer adherent cells derived from multiple OSCC cell lines." (PMID 37759448, 2023). "More studies focused Orai3 and found that Orai3 promoted cell proliferation and enhanced apoptosis resistance in tumour cells." (PMID 36128650, 2022). "Our data demonstrate that Orai3 silencing in PC cells decreases cell proliferation and cell migration thereby inhibiting tumor growth and secondary metastasis in vivo." (PMID 34885048, 2021). "Most importantly, our in vivo xenograft studies demonstrate a critical role of Orai3 in PC tumor growth and secondary metastasis." (PMID 34885048, 2021). "In summary, this suggests that Orai3 regulates PC tumor growth at least in part by controlling cell-cycle progression." (PMID 34885048, 2021). "Earlier work from our group and others have demonstrated that Orai3 plays an important role in tumor progression in vivo." (PMID 34885048, 2021). "Collectively, the in vivo data elegantly demonstrate that Orai3 plays a crucial role in PC progression and tumor growth." (PMID 34885048, 2021). "Orai3 can be activated by arachidonic acid, production of which is upregulated during tumor progression." (PMID 32575848, 2020). "Not only the main players of SOCE, STIM1 and Orai1, but also the slightly “neglected” STIM2 and Orai3 are involved in proliferation and growth of tumor cells." (PMID 30935064, 2019). "The study reports an oncogenic switch in which cells, especially those exposed to tumor microenvironmental factors (here, arachidonic acid), change from homologous Orai1 complexes to more heterogeneous Orai1–Orai3 complexes by upregulating Orai3 expression." (PMID 30935064, 2019). "Next, we investigated the correlation of ORAI3/ORAI1 ratio with CRC progression by studying its variation according to tumor stages." (PMID 31010205, 2019). "The expression of Orai3 has been evaluated using immunohistochemistry, which is the more relevant technique for heterogeneous tumour." (PMID 27835593, 2016). "We also assessed correlations of the Orai3 expression with clinical parameters (age, sex, tumor size, nodal metastasis, vessel invasion, TNM)." (PMID 24058448, 2013). "In several neoplasms, ORAI3 appears to supersede ORAI1 in functional relevance." (PMID 41596760, 2026). "Importantly, ORAI3 is preferentially upregulated in malignant cells of breast, prostate, lung, and gastrointestinal origin but remains low in non-tumor tissue." (PMID 41596760, 2026). "In CRC cells Orai3 has been reported to be upregulated and is involved in tumor progression." (PMID 38514909, 2024). "Subsequently, Orai3 was reported to contribute to prostate and more recently to PC tumor growth." (PMID 34885048, 2021).
tumor (continued). "Our in vivo data elegantly demonstrates a critical role of Orai3 in PC tumor growth and metastasis." (PMID 34885048, 2021). "Therefore, we used GFP-tagged stable Orai3 silenced Panc1 cells for evaluating the role of Orai3 in primary tumor growth and secondary metastatic spread." (PMID 34885048, 2021). "The authors speculated that the increase in Orai3 expression and/or change in the tumour microenvironment (arachidonic acid) led to the recruitment of Orai1 subunits into the assembly of heteropentameric Orai1/Orai3 ARC channels." (PMID 32825277, 2020). "Functional assays revealed that mCRC cell proliferation and migration are not affected in Stim1-, Orai1- and Orai3-deficient cells, thereby confirming that Stim and Orai proteins do not mediate tumor growth and metastases in patients-derived CRC cells." (PMID 30123430, 2018). "For instance, Orai3 was found to up-regulated in several types of T-ECFCs, but its role in tumor vascularization is currently unknown." (PMID 29324706, 2018). "Finally, our results clearly show that Orai3 channels are expressed in both normal and tumor lung tissues." (PMID 24058448, 2013). "Moreover, Orai3 is overexpressed in tumoral lung tissues compared to normal ones, and correlates with high tumor grade." (PMID 24058448, 2013). "In addition, further studies in tumor MiaPaCa2 cells indicate that Orai3 knockdown impairs cell survival and induces mitotic catastrophe and apoptosis, as well as inhibits tumor growth and induces apoptosis in vivo using nude mice bearing MiaPaCa2-derived xenografts." (PMID 34768857, 2021). "Interestingly, Orai3 staining was found to be more elevated in higher tumor grades." (PMID 34768857, 2021). "Hence, ORAI3 may be of particular significance in the tumor microenvironment where hypoxia can contribute to increased levels of ROS." (PMID 30754719, 2019). "Moreover, the expression of Orai3 increases in high tumor grade." (PMID 24058448, 2013). "Similar to the enrichment of Orai3 in CSCs, ID1 exhibited elevated expression levels in tumor spheres in comparison to their corresponding monolayer adherent cells." (PMID 37759448, 2023). "Herein, we provided the evidence that Stim1-2, Orai1 and Orai3 proteins mediate constitutive Ca2+ entry in both primary and metastatic CRC cells deriving from human tumor samples." (PMID 30123430, 2018). "The Orai3 channel was found to be overexpressed in tumor lung tissues when compared to nontumoral ones and its expression was correlated with higher tumor grades." (PMID 34065942, 2021). "Moreover, the expression of TRPC1, ORAI1, ORAI2, ORAI3 and STIM1 was increased in tumor cells in contrary to STIM2 protein which was found to be depleted." (PMID 31010205, 2019). "A strong staining of Orai3 was observed in 66.7% of tumor samples as compared to the non-tumoral samples (40/60, p<0.001)." (PMID 24058448, 2013). "Indeed, Orai3 increased the cell proliferation capacity in vivo; however, Orai3 failed to endow the cells with full tumor-forming ability in vivo." (PMID 37759448, 2023). "Interestingly, although the genes individually did not correlate with tumor progression, the ORAI3/ORAI1 Ratio was significantly increased in stages III and IV compared to Stage I in both TCGA and GSE39582 datasets." (PMID 31010205, 2019). "Among the 200 cases of tumour tissues matched with non-tumour tissues tested, the score of Orai3 staining in tumour tissues was higher than in matched non-tumour ones (non-tumour tissues: 0.3 ± 0.04 vs. tumour tissues: 0.66 ± 0.005, p<0.05; Wilcoxon signed-rank test)." (PMID 27835593, 2016).
adenocarcinoma (3 papers, 2013 to 2021). A common cancer characterized by the presence of malignant glandular cells. "However, the activation mode of Orai3 seems to be different in these cell lines although they are both adenocarcinomas." (PMID 34065942, 2021). "Since its role in proliferation and its increased expression in NSCLC samples, Orai3 may thus be a potential target for adenocarcinoma lung therapy." (PMID 24058448, 2013). "In conclusion, our study highlights Orai3 as a major regulator of cell cycle progression and therefore growth of NSCLC cells and makes it as an interesting potential bio-marker and/or target for adenocarcinoma lung therapy." (PMID 24058448, 2013).
infection (1 paper, 2013). The state of being infected such as from the introduction of a foreign agent such as serum, vaccine, antigenic substance or organism. "Knockdown of Orai3 transcripts however required the use of a multiplicity of infection (moi) of adenovirus (moi 250), significantly higher than that required to achieve knockdown of Orai1 and Orai2 transcripts (moi 100)." (PMID 24040356, 2013). "While HLMCs transduced with shRNA against Orai3 or luciferase appeared viable morphologically and by Trypan blue exclusion, the high multiplicity of infection required reduced FcεRI-dependent mediator release in the luciferase shRNA control." (PMID 24040356, 2013).
ORAI3 also shares sentences with these, for which no sentence is quoted: psoriatic arthritis (2 papers); acute myeloid leukemia (1); atherosclerosis (1); brain injury (1); breast adenocarcinoma (1); dementia (1); esophageal tumor (1); immunodeficiencies (1); large cell carcinoma (1); lymph node metastatic tumors (1); myelofibrosis (1); Obesity (1); Oropharyngeal Cancer (1); pancreas carcinoma (1); papillary adenocarcinoma (1); parathyroid adenoma (1); preeclampsia (1); Stroke (1); systemic lupus erythematosus (1).